KMT2A (lysine methyltransferase 2A)
Diseases named in the same sentence as KMT2A in open-access papers (continued):
Sharing a sentence is not in itself a finding about the gene and the disease.
leukemia (continued). "In children, midostaurin has been investigated as monotherapy in r/r pediatric leukemia, including KMT2A-rearranged ALL or FLT3-mutated AML (NCT0866281), which unfortunately demonstrated limited efficacy in the 22 enrolled participants (the trial terminated early due to lack of enrollment)." (PMID 32050659, 2020). "Are mutations in PI3K/RAS pathway second hits for early KMT2A-leukemia onset?" (PMID 31723831, 2019). "Among the better-known activities of KMT2A is the regulation of the Hox gene cluster, which is implicated in the control of normal hematopoiesis and whose dysregulation is often associated with the development of leukemia." (PMID 30126100, 2018). "Importantly, the oncogenic function of MLL fusion proteins in leukemia is critically dependent upon their association with the scaffolding protein menin, a partner protein of MLL1 and MLL4 (i.e. KMT2A and KMT2B) in the TrxG COMPASS-like complexes." (PMID 27888797, 2017). "Indeed, several dietary bioflavonoids induce cleavageof KMT2A, and epidemiological studies indicate an elevated risk of leukemia ininfants exposed in utero to DNA-damaging drugs, herbal medicines,dipyrone, and mosquitocidals." (PMID 26657054, 2015). "However,etoposide induces chemotherapy-associated secondary leukemia, which involvesrearrangement of the KMT2A (MLL) gene onchromosome 11q23." (PMID 26657054, 2015). "Similar to KMT2A‐fusion driven disease, leukemia cell proliferation and self‐renewal as well as the underlying gene‐expression program could be abrogated by genetic inactivation of KMT2A or MEN1 as well as by the pharmacologic inhibition of the KMT2A–Menin interaction." (PMID 39887730, 2026). "However, the CBL0137/panobinostat combination did not induce significant changes in the levels of acetylation or methylation of specific histones associated with KMT2A-r leukemia or in the expression levels of leukemogenic KMT2A target genes such as HOXA9 and MEIS1 before induction of apoptosis." (PMID 35677155, 2022). "Lineage switching of leukemias may also occur; for example, leukemia associated with the KMT2A/AFF1 fusion gene, which commonly presents as pediatric B cell precursor ALL, may also demonstrate an infant B/myeloid mixed phenotype or relapse with the original clone switching to AML." (PMID 35409034, 2022). "These patterns suggest that KMT2A fusion proteins activate distinct oncogenic networks within different cells of the same tumor and may explain the lineage plasticity associated with KMT2Ar leukemia." (PMID 34663924, 2021). "However,activation of cellular proliferation by mutation of other genes associated withcellular proliferation as well as KMT2A rearrangement might benecessary for the full development of leukemia." (PMID 26657054, 2015). "KMT2A is affected by gain‐of‐function mutations in various cancers and by chromosomal translocations leading to the formation of oncogenic fusion proteins in the so‐called KMT2A‐rearranged leukemias (KMT2A‐r), a distinct leukemia subtype." (PMID 40181550, 2026). "Accumulating evidence further demonstrated that other drivers of leukemia also hijack WT‐Menin‐KMT2A complexes in a similar way to drive HOX/MEIS1 gene expression." (PMID 39887730, 2026). "Given that DOT1L's methyltransferase activity is not required in normal tissues, its pharmacological inhibition represents a highly selective therapeutic strategy in the context of KMT2A‐rearranged and other KMT2A‐dependent leukemias." (PMID 40181550, 2026). "KMT2A::MLLT3 is among the most common translocations initiating leukaemia in infants, where it can manifest with a myeloid or lymphoid leukaemia phenotype." (PMID 41545699, 2026). "Of note, also these subtypes of leukemia are sensitive to genetic and pharmacologic disruption of the Menin‐KMT2A complex." (PMID 39887730, 2026).
leukemia (continued). "Aberrant activation of KMT2A‐target genes, part of a conserved stem‐cell program, is driven by KMT2A‐fusion oncogenes or activated by wild‐type KMT2A complexes as demonstrated specifically in NPM1mut leukemias." (PMID 40181550, 2026). "In contrast to KMT2A‐fusion complexes in leukemia, the relevance of WT‐KMT2A/Menin complexes remain controversial in many cancer types." (PMID 39887730, 2026). "The most frequent KMT2A alterations in leukemia are in fact gene amplifications of KMT2A followed by gene fusions." (PMID 39887730, 2026). "KMT2A‐rearranged leukemia cells on the other hand are highly addicted to DOT1L for the maintenece of oncogenic gene expression." (PMID 39887730, 2026). "Recent work in a leukemia model system in which the KMT2A::MLLT3 oncogene was expressed fused to a degron‐tag, for the first time shed light on the hierarchy of chromatin‐related versus transcription‐related events at KMT2A‐fusion bound genes." (PMID 39887730, 2026). "In preclinical models, various Menin inhibitors have now shown remarkable effectiveness in treating KMT2A‐rearranged, NPM1‐mutated, and NUP98‐rearranged leukemia." (PMID 39887730, 2026). "Based on these promising results in this difficult‐to‐treat patient cohort, Revumenib received breakthrough designation from the FDA and was approved for the treatment of relapsed or refractory leukemia with KMT2A‐rearrangements by the FDA in November 2024." (PMID 39887730, 2026). "Several labs have recently set-up such CRISPR/Cas9 experiments for different KMT2A translocation and have used this novel technology to create experimental model systems in order to study particular types of leukemia diseases." (PMID 41145673, 2026). "In KMT2Ar leukemias, the menin–KMT2A interaction is essential for nuclear translocation and transcriptional activation of leukemogenic programs." (PMID 40710017, 2025). "KMT2A-rearranged leukemias characteristically exhibit marked upregulation of homeobox A (HOXA) genes, especially HOXA9, which are central to leukemic transformation." (PMID 40374809, 2025). "An important subtype of acute leukemia is the MLL1-rearranged leukemia (MLL1r), characterized by chromosomal translocations involving the MLL1 (KMT2A) gene." (PMID 40723215, 2025). "Treatment with Pinometostat in KMT2A-rearranged cells and xenograft models reduced H3K79me2 levels, leading to decreases expression of KMT2A target genes and selective cytotoxicity toward leukemia cells." (PMID 40361241, 2025). "Rearrangements of lysine methyltransferase 2A (KMT2A, also known as mixed lineage leukemia (MLL)) are prevalent in about 23% of t-AML, which is characterized by heterogeneity and chemotherapy resistance." (PMID 40362245, 2025). "In connection with these data, KMT2A::AFF1 fusion protein promotes leukemia progression mainly by activating pro-leukemogenic factors HOXA9 and MEIS1." (PMID 40722046, 2025). "Targeting the wild-type (WT) KMT2A protein in KMT2A-r leukemia represents a promising therapeutic approach, garnering increasing interest in current research." (PMID 40361241, 2025). "DOT1L, the sole histone H3K79 methyltransferase, is co-opted by KMT2A (MLL) fusion complexes to sustain HOXA/MEIS transcriptional circuitry in KMT2A-rearranged leukemias." (PMID 41347170, 2025). "In vivo, the study showed that the overexpression of miR-30e delays the development of KMT2A::MLLT3-driven leukemia." (PMID 40282406, 2025). "KMT2A-rearranged AMLs represent 5–10% of adult AMLs, but are much more frequent in younger patients; in these leukemias, the rearrangement of the KMT2A gene upregulates HOX-MEIS1 expression." (PMID 40227641, 2025). "Menin is a critical co‐factor of KMT2A, and menin inhibitors are a novel and promising treatment option in KMT2A‐r leukemias." (PMID 39754404, 2025). "KMT2A fusion proteins act highly transformative and are often used to initiate leukemia with a high frequency of self-renewing cells being a valuable model to study LSCs." (PMID 39870768, 2025).
leukemia (continued). "A prominent example of epigenetic dysregulation in AML, that has greatly educated the field, is provided by leukaemias with MLL (Mixed Lineage Leukaemia, also known as KMT2A) gene rearrangements." (PMID 40651916, 2025). "This approach uncovered a distinct fetal pre-leukemic state and identified a transcriptional signature transferable to human KMT2A::AFF1 leukemia." (PMID 40646135, 2025). "The interaction between KMT2A fusion proteins and Menin is crucial for the development of KMT2A-r leukemia, as Menin is a necessary cofactor for KMT2A binding to HOX gene promoters." (PMID 40361241, 2025). "Rearrangements of the histone lysine [K]-methyltransferase 2A gene (KMT2A), formerly known as the mixed-lineage leukemia (MLL) gene and located on chromosome 11q23, are commonly observed in acute lymphoblastic leukemia (ALL)." (PMID 41333696, 2025). "In experimental models, enforced expression of the KMT2A–AF9 fusion is sufficient to induce leukemia, highlighting the strong oncogenic potential of KMT2A fusion proteins." (PMID 41153634, 2025). "This critical dependency on the Menin-KMT2A interaction has been identified as a key therapeutic vulnerability across nearly all KMT2A-r leukemias." (PMID 41614752, 2025). "KMT2A-germline pediatric ALLs are usually less commonly associated with high WBC and central nervous system (CNS) leukemia at presentation." (PMID 40584390, 2025). "For example, leukemias harboring certain KMT2A rearrangements can have a dismal prognosis, with a 5-year event free survival less than 30%." (PMID 40707674, 2025). "FLT3 mutations (D835 and ITD) are detected in patients with leukemia with mixed-lineage leukemia-rearrangement (MLL-r), caused by a translocation of H3K4 methyltransferase (H3K4HMT) MLL1 (also known as KMT2A)." (PMID 40341256, 2025). "In particular, KMT2A::AFF1 ALL, an aggressive leukemia with a poor prognosis and a low mutational burden, exhibits substantial transcriptional heterogeneity between individuals." (PMID 40729681, 2025). "NUP98, located on chromosome 11p15, interacts with the histone methyltransferase NSD1, and preclinical studies have demonstrated that these leukemias are dependent on KMT2A activity, which can be disrupted through menin inhibition." (PMID 40710017, 2025). "The most common form of IL is characterized by cytogenetically balanced chromosomal translocations that include the mixed-lineage leukemia gene (KMT2A gene previously named as MLL) on chromosome 11q23, first described in 1991–1992." (PMID 41153599, 2025). "Among the most challenging of these are leukemias driven by rearrangements of the KMT2A gene (KMT2A-r), located at chromosome 11q23." (PMID 41614752, 2025). "The investigation of these novel modalities has the potential to facilitate the development of more effective treatments for patients with KMT2A-related leukemias and other cancers that are influenced by KMT2A aberrations." (PMID 40361241, 2025). "Revumenib (SNDX‐5613) is a potent, oral, small‐molecule inhibitor of the menin–KMT2A complex, which in single‐agent early Phase 1 and 2 trials showed impressive safety and efficacy in patients with R/R KMT2A‐r leukemias." (PMID 40698850, 2025). "This is driven by the intrinsic resistance of the KMT2A-driven leukemia stem cell (LSC) population, which can survive initial chemotherapy and re-initiate the disease." (PMID 41614752, 2025). "KMT2A-fusion proteins, resulting from rearrangements of the KMT2A gene, are central to the pathogenesis of KMT2Ar leukemias." (PMID 39682203, 2024). "KMT2A fusions have been reported in 3% of primary pediatric and adult leukemia, as well as 10% of secondary leukemia, occurring following treatment with DNA topoisomerase II inhibitors." (PMID 38730645, 2024). "KMT2A(lysine methyltransferase 2A)-rearranged acute leukemia is a class of leukemia with unique biological characteristics with moderate or poor prognosis." (PMID 38964931, 2024).
leukemia (continued). "Menin inhibitors show significant clinical efficacy against KMT2A-rearranged and NPM1-mutated acute leukemias, with promising potential to address unmet needs in various pediatric leukemia subtypes." (PMID 39179671, 2024). "These combination approaches aim to disrupt key oncogenic pathways, reduce resistance, and enhance treatment efficacy, ultimately providing more durable remissions and improved survival for patients with KMT2A-rearranged leukemias." (PMID 39682203, 2024). "Menin inhibitors have emerged as a promising therapeutic strategy by specifically targeting the critical menin–KMT2A interaction that drives the oncogenic transcriptional programs in these leukemias." (PMID 39682203, 2024). "Targeting the WT KMT2A protein in KMT2A-r leukemia is a therapeutic approach also gathering increasing interest." (PMID 39303915, 2024). "In NPM1mt leukemia, the interaction between menin and KMT2A is crucial for the binding of mutant NPM1c to chromatin." (PMID 39682203, 2024). "Another mechanism involves a lineage switch in patients with KMT2A (lysine methyltransferase A2) rearrangements in mixed lineage leukemia-rearranged ALL." (PMID 38339258, 2024). "KMT2A-rearranged leukemias are a highly aggressive subset of acute leukemia, characterized by poor prognosis and frequent relapses despite intensive treatment." (PMID 39682203, 2024). "Combining menin inhibitors with depletion of IGF2BP3 impairs cell growth and increases differentiation of KMT2A::AFF1 leukemia." (PMID 38601080, 2024). "Aberrant expression of HOX and MEIS1 family genes, as seen in KMT2A-rearranged, NUP98-rearranged, or NPM1-mutated leukemias leads to arrested differentiation and leukemia development." (PMID 39179671, 2024). "The trial was later amended to limit enrollment to patients with KMT2A-r or NPM1-m leukemia because preclinical data demonstrated the efficacy of targeting the KMT2A-menin interaction." (PMID 39179671, 2024). "Abnormalities in the KMT2A gene occur in 70–80% of cases of infant leukemia, and they are rarely found in older AML patients." (PMID 39590121, 2024). "KMT2A-rearranged leukemia (KMT2Ar, former MLLr) is a chromosomal translocation resulting in the development of chimeric fusion genes and proteins with oncogenic potential." (PMID 38030791, 2024). "KMT2A‐r‐ALL and KMT2A‐r‐AML are two distinct subtypes of leukemia, each distinguished by KMT2A rearrangements on a genomic level." (PMID 39428967, 2024). "The most common fusion partner, AFF1 (AF4), followed by MLLT3 (AF9), MLLT1 (ENL), and MLLT10 (AF10), account for a large majority of observed cases of KMT2A-r leukemias." (PMID 39303915, 2024). "KMT2A (also known as MLL), located on chromosome 11q23, is frequently rearranged in pediatric and adult leukemias across different lineages." (PMID 39766092, 2024). "The partner genes that fuse with the KMT2A gene vary in different cases of leukemia, and the specific fusion partner can impact the disease's characteristics and prognosis." (PMID 39428967, 2024). "The two most important aberrantly expressed genes in KMT2A-rearranged leukemias are HOXA9 and MEIS1 since their upregulation was shown to be crucial for leukemogenesis." (PMID 39834944, 2024). "Infant and adult MLL1/KMT2A-rearranged (MLLr) leukemia represents a disease with a dismal prognosis." (PMID 38555405, 2024). "Genetic screening of bone marrow for 57 types of leukemia identified a positive KMT2A/AFF1 fusion gene." (PMID 39717192, 2024). "Depletion of the murine paralog IGF2BP3 increases the latency of leukemia in murine models of KMT2A::AFF1 AML." (PMID 38601080, 2024). "The resulting KMT2A fusion genes give rise to chimeric fusion proteins representing strong oncogenic drivers of leukemia development." (PMID 38892207, 2024). "KMT2A‐rearranged (KMT2A‐r) leukemia is characterized by a rapid onset, aggressive progression, and significantly worse prognosis compared to non‐KMT2A‐r leukemias." (PMID 39428967, 2024).
leukemia (continued). "Menin inhibitors have entered clinical evaluation and have shown remission-inducing activity in some patients with KMT2A fusion leukemias." (PMID 39510293, 2024). "Central to KMT2A‐r leukemia are KMT2A fusion proteins, which are the product of chromosomal translocations." (PMID 39428967, 2024). "Studies indicate that KMT2A rearrangements are present in over 70% of infant leukemia cases, approximately 10% of adult AML cases, and numerous instances of secondary acute leukemias, making it a disease of critical concern to clinicians and researchers alike." (PMID 39428967, 2024). "Lysine-specific N-methyltransferase 2A (KMT2A), also known as mixed-lineage leukemia (MLL), is the target of balanced rearrangements." (PMID 39201709, 2024). "Two subgroups of KMT2A-rearranged leukemia have been described: ones characterized by translocations with other genes, and one characterized by partial tandem duplications (PTDs)." (PMID 39201709, 2024). "Studies show that inhibiting the menin–KMT2A interaction can lead leukemia cells to shift their transcriptional programs, compensating for the lost interaction." (PMID 39682203, 2024). "KMT2A-rearranged leukemias are an aggressive form of leukemia with high relapse rates, even after intensive treatment." (PMID 39682203, 2024). "HOXA9 plays a key role in KMT2A-rearranged (KMT2A-r) leukemia, mediated by binding of the KMT2A fusion protein to HOX gene promoters and recruitment of DOT1L H3K79 methyltransferases." (PMID 38601080, 2024). "In effect, the fusion of 11q23 with greater than 100 distinct partner genes occurs in KMT2A‐r leukemias, resulting in various KMT2A fusion proteins." (PMID 39428967, 2024). "Acute leukemias in ~75% infant and 5–10% child/adult patients are caused by chromosomal translocations of mixed lineage leukemia (MLL, also known as MLL1 or KMT2A) gene, which generate oncogenic fusion MLL (onco-MLL)." (PMID 37958457, 2023). "Barabe and colleagues showed that retroviral expression of the KMT2A::ENL fusion gene itself is sufficient to initiate leukemogenic programs in primary human HSPCs to induce leukemia in vivo." (PMID 38201282, 2023). "Despite this, targeting DOT1L remains a promising avenue for treating KMT2A rearranged leukemias, and novel small-molecule DOT1L inhibitors with improved PK profiles have already been identified." (PMID 37740239, 2023). "An example of this are acute leukemias with KMT2A (MLL) gene rearrangements, which are responsible for approximately 10% of adult human leukemias." (PMID 37886034, 2023). "In preclinical models of KMT2A-r leukemia these molecules disrupt the menin-KMT2A interaction and inhibit the chromatin occupancy of menin and KMT2A at select KMT2A target genes leading to pronounced suppression of predominantly MEIS1, but also HOXA genes." (PMID 38174649, 2023). "KMT2A-D are alternatively termed mixed lineage leukemia proteins (MLL1-4), due to KMT2A/MLL1 originally being identified as a frequent breakpoint in mixed lineage leukemia (MLL)." (PMID 36598580, 2023). "KMT2A is a frequent target for recurrent translocations in acute myeloid leukemia (AML), acute lymphoblastic leukemia (ALL), or mixed lineage (biphenotypic) leukemia (MLL)." (PMID 36979800, 2023). "Our studies uncover a selective dependency of KMT2A-rearranged (KMT2A-r) leukemias on proteostasis and specifically immunoproteasome function." (PMID 38049829, 2023). "Rearrangements of the Mixed Lineage Leukemia (MLL, also known as KMT2A) gene (MLLr) cause aggressive, poor prognosis acute lymphoblastic (ALL) and acute myeloid (AML) leukemias in both children and adults and are associated with very few cooperating mutations." (PMID 37626123, 2023). "Identification and validation of immunoproteasome function for the first time as a cell intrinsic target across KMT2A-complex dependent leukemias creates a unique functional KMT2A-r and NPM1c AML specific dependency, limiting LSC self-renewal." (PMID 38049829, 2023).